EXOSC7 (exosome component 7)
Description:
Non-catalytic component of the RNA exosome complex which has 3'->5' exoribonuclease activity and participates in a multitude of cellular RNA processing and degradation events. In the nucleus, the RNA exosome complex is involved in proper maturation of stable RNA species such as rRNA, snRNA and snoRNA, in the elimination of RNA processing by-products and non-coding 'pervasive' transcripts, such as antisense RNA species and promoter-upstream transcripts (PROMPTs), and of mRNAs with processing defects, thereby limiting or excluding their export to the cytoplasm. The RNA exosome may be involved in Ig class switch recombination (CSR) and/or Ig variable region somatic hypermutation (SHM) by targeting AICDA deamination activity to transcribed dsDNA substrates. In the cytoplasm, the RNA exosome complex is involved in general mRNA turnover and specifically degrades inherently unstable mRNAs containing AU-rich elements (AREs) within their 3' untranslated regions, and in RNA surveillance pathways, preventing translation of aberrant mRNAs. It seems to be involved in degradation of histone mRNA. The catalytic inactive RNA exosome core complex of 9 subunits (Exo-9) is proposed to play a pivotal role in the binding and presentation of RNA for ribonucleolysis, and to serve as a scaffold for the association with catalytic subunits and accessory proteins or complexes.
Synonyms: KIAA0116; RRP42; hRrp42p; Rrp42p; EAP1; p8
Tractability: Small molecule: a structure with a bound ligand is known. PROTAC: ubiquitination databases record sites on it; its protein half-life has been measured.
Gene: Protein-coding gene on chromosome 3 (44,975,241 to 45,036,066, forward strand). Ensembl gene ENSG00000075914.
Subcellular location: Nucleus, nucleolus; Cytoplasm; Nucleus
Subcellular location (Human Protein Atlas): Nuclear speckles
Pathways (Reactome):
Metabolism of RNA: Butyrate Response Factor 1 (BRF1) binds and destabilizes mRNA; KSRP (KHSRP) binds and destabilizes mRNA; Major pathway of rRNA processing in the nucleolus and cytosol; Nuclear RNA decay; Tristetraprolin (TTP, ZFP36) binds and destabilizes mRNA; mRNA decay by 3' to 5' exoribonuclease
Cellular responses to stimuli: ATF4 activates genes in response to endoplasmic reticulum stress
Gene Ontology:
Molecular function: protein binding; RNA exonuclease activity; 3'-5'-RNA exonuclease activity; mRNA 3'-UTR AU-rich region binding; RNA binding
Biological process: RNA catabolic process; RNA processing; exonucleolytic trimming to generate mature 3'-end of 5.8S rRNA from tricistronic rRNA transcript (SSU-rRNA, 5.8S rRNA, LSU-rRNA); nuclear mRNA surveillance; nuclear polyadenylation-dependent rRNA catabolic process; rRNA catabolic process; rRNA processing; TRAMP-dependent tRNA surveillance pathway; U1 snRNA 3'-end processing; U4 snRNA 3'-end processing; U5 snRNA 3'-end processing
Cellular component: cytosol; exosome (RNase complex); nuclear speck; nucleolus; nucleus; cytoplasmic exosome (RNase complex); nuclear exosome (RNase complex); nucleolar exosome (RNase complex); nucleoplasm; cytoplasm; exoribonuclease complex
Genetic constraint (gnomAD): Loss-of-function variants: 19 observed, 27.56 expected, observed/expected ratio (o/e) 0.69, 90% interval 0.48 to 1.01. The upper end of that interval is the gene's LOEUF score, 1.01, which puts it in group 4 of 6, group 1 being the genes least tolerant of losing a copy. Missense variants: 326 observed, 329.56 expected, observed/expected ratio (o/e) 0.99, 90% interval 0.9 to 1.08. Synonymous variants: 111 observed, 127.86 expected, observed/expected ratio (o/e) 0.87, 90% interval 0.74 to 1.02.
Homologues: Orthologues: chimpanzee EXOSC7 (99% identical), dog EXOSC7 (97% identical), mouse Exosc7 (96% identical), macaque EXOSC7 (94% identical), guinea pig EXOSC7 (92% identical), rat Exosc7 (90% identical), pig EXOSC7 (84% identical), rabbit EXOSC7 (79% identical), zebrafish exosc7 (75% identical), tropical clawed frog exosc7 (74% identical), Drosophila melanogaster Rrp42 (48% identical), Caenorhabditis elegans exos-7 (36% identical). Paralogues in human: EXOSC9 (27% identical), EXOSC8 (26% identical).
Diseases named in the same sentence as EXOSC7 in open-access papers:
EXOSC7 is named in the same sentence as 5 diseases in open-access papers, as found by Europe PMC text mining. Sharing a sentence is not in itself a finding about the gene and the disease. The quoted sentences say what the papers report.
COVID-19 (1 paper, 2023). A disease caused by infection with severe acute respiratory syndrome coronavirus 2. "Like EXOSC2, higher expression levels of EXOSC7 and EXOSC9 are significantly associated with higher risk for clinical COVID-19 (P < 0.05)." (PMID 36241425, 2023).
diabetic foot ulcers (1 paper, 2025). "Our study found that EXOSC7 was associated with proteasome pathways that underwent activity changes under hyperglycemic conditions, potentially leading to microvascular damage —a key factor contributing to poor healing in diabetic foot ulcers." (PMID 40722759, 2025).
EXOSC7 also shares sentences with these, for which no sentence is quoted: infection (1 paper); mantle cell lymphoma (1); oral cancer (1).